MUC16 (mucin 16, cell surface associated)
Diseases named in the same sentence as MUC16 in open-access papers (continued):
Sharing a sentence is not in itself a finding about the gene and the disease.
ovarian carcinoma (continued). "For example, previous research has identified a series of mucins aberrantly secreted by ovarian cancer cells, including MUC1, MUC2, MUC4, MUC13, MUC16, and MUC20." (PMID 36553184, 2022). "In epithelial ovarian cancers, PTX bubbles containing the MUC16 antibody can effectively inhibit resistance to PTX." (PMID 35745854, 2022). "MUC16 (CA125) is the largest transmembrane mucin, which is highly glycosylated and reportedly promotes ovarian cancer." (PMID 36482940, 2022). "Current strategies for epithelial ovarian cancer (EOC) screening use a combination of blood-based biomarkers, notably cancer antigen 125 (CA125; mucin 16 (MUC16)) and human epididymis protein (HE)-4, and trans-vaginal ultrasound imaging." (PMID 35031764, 2022). "We have previously demonstrated co-immunoprecipitation of Gal3, MUC16, and Epidermal Growth Factor receptor (EGFR) protein and showed co-localization of the three proteins in ovarian cancer explants and human ovarian cancer sections." (PMID 33580170, 2021). "In patients with ovarian cancer (n = 61), serum levels of ALCAM are higher than controls and significantly correlated with protein marker CA125/MUC16." (PMID 34680335, 2021). "Folate receptor alpha, mesothelin, MUC16, TROP2, tissue factor, and NaPi2b are common antigens used for conjugation in this malignancy, as they are usually overexpressed in epithelial ovarian cancer." (PMID 32784819, 2020). "Mucin 16 (MUC16, also known as CA125) is an ovarian cancer antigen over-expressed by a majority of EOC." (PMID 33322601, 2020). "Mucin 16 (MUC16), the protein source of cancer antigen 125 (CA-125) facilitates peritoneal metastasis of ovarian cancer and contributes to the immune suppressive tumor microenvironment by inhibiting the activity of NK cells." (PMID 32780245, 2020). "Selectin ligands that have been targeted for therapeutic intervention in ovarian cancer include MUC1 and MUC16." (PMID 32785160, 2020). "Phase I/II clinical trials are currently in progress in order to investigate CAR-T cells targeting MUC16 (NCT02498912), mesothelin (NCT01583686), and NY-ESO-1 (NCT01567891 and NCT02457650) for ovarian cancer." (PMID 33123161, 2020). "From 2000 to 2015, there were 13 clinical trials with 148 patients receiving DC immunotherapy for ovarian cancer targeting antigens that included MUC1, MUC16, HER2, and FOLR1, with variable and inconsistently reported results." (PMID 32937961, 2020). "We collect 94 ovarian cancer (OC) patients’ tissue samples to constitute tissue microarray (TMA) and analyze the MUC16 and p120ctn expression levels." (PMID 30795761, 2019). "Its strong interaction with MUC16 (CA125), a large membrane-spanning glycoprotein, contributes to peritoneal spread in ovarian cancer by promoting heterotypic cell adhesion and increases the motility and invasiveness of pancreatic cancer cells." (PMID 31354732, 2019). "For example, they found low levels of certain markers that have been gaining traction as drug targets (EphA2), or that have been touted as specific for (MUC16 and FOLR1) or overabundant (Mesothelin) in ovarian cancer." (PMID 30011875, 2018). "Our study provides a novel gene delivery system using a MUC16 promoter trigger and FSH peptide-mediated active targeting for ovarian cancer." (PMID 29542355, 2018). "CA125, a repeating peptide epitope of the mucin 16 (MUC16), is a large membrane-bound cell surface mucin, discovered in 1981 by a monoclonal antibody OC125 developed from mice immunized with human ovarian cancer cells." (PMID 30134520, 2018).
ovarian carcinoma (continued). "Carbohydrate antigen 125 or mucin 16 (MUC16) is a glycoprotein that is overexpressed in different types of cancers, although it is mainly used as a biomarker for the early prognosis of ovarian cancer." (PMID 29527514, 2018). "Expression analysis of MUC1, MUC16, and TAG72 on patient samples from various epithelial subtypes of ovarian cancer highlights antigen heterogeneity in this disease and demonstrates the aberrant expression pattern of cell-surface glycoproteins." (PMID 30510550, 2018). "In addition to ovarian cancer, MUC16 may be a candidate biomarker for lung cancer." (PMID 29552305, 2018). "Mucin 16 (MUC16), more commonly referred to as CA125, is the biomarker primarily used to monitor ovarian cancer recurrence and for differential diagnosis of pelvic masses." (PMID 29051715, 2017). "MUC16/CA125 has been identified as a prominent cancer biomarker, especially for epithelial ovarian cancers, in clinical test for over three decades." (PMID 27167110, 2016). "MUC16, initially named cancer antigen 125 (CA125), was first described as a biomarker in a screen of monoclonal antibodies developed against the OVCA433 ovarian cancer cell line." (PMID 26509158, 2015). "The importance of MUC16/CA125 in the diagnosis, progression and therapy of ovarian cancer warrants the need for in-depth research on the biochemistry and biology of this mucin." (PMID 24886523, 2014). "The strong interaction between MUC16 and mesothelin, a glycosylphosphatidylinositol- (GPI-) anchored glycoprotein, promotes cell adhesion and peritoneal metastasis of ovarian cancer cells." (PMID 22481932, 2012). "At present, MUC1 and MUC16 are the best and only characterized mucins and monoclonal antibodies against MUC1 and MUC16 are under preclinical and clinical investigations for ovarian cancer treatment." (PMID 20034397, 2009). "In particular, a combined panel of MUC4, MUC5AC, and MUC16 may offer an effective and reliable diagnostic system and target for the management of various histological grades and types of ovarian cancer, although their biological functions are not clearly defined." (PMID 20034397, 2009). "The data presented conclusively shows that mesothelin binds to native MUC16 expressed by the ovarian cancer cell line OVCAR-3 and also to MUC16 isolated from the peritoneal fluid of patients with EOC." (PMID 17067392, 2006). "In addition, researchers evaluated DMUC4064A, a newer generation anti-MUC16 ADC, in a phase I study (NCT02146313) of patients with platinum-resistant ovarian cancer." (PMID 40722601, 2025). "Reassuringly, the presence of anti-MUC16 antibodies did not accelerate hypoxia-induced downregulation in our ovarian cancer models." (PMID 41413213, 2025). "Notably, cancers such as melanoma, AML, and ovarian cancer harbor uniquely expressed genes, including well-characterized immunotherapy targets like PRAME, MPO and MUC16." (PMID 40672284, 2025). "Phosphorylation of S6 and 4EBP1 as downstream effector molecules involved in translational regulation of the phosphatidylinositol 3'-kinase (PI3K)/AKT pathway was reduced in ovarian cancer cell lines with MUC16 knockout, but not in breast cancer." (PMID 38758220, 2024). "Additionally, multiplexed magnetic nanoparticle-antibody conjugates combining MUC16, B2M, and APOA1 achieved high sensitivity (94%) and specificity (98%) in distinguishing early-stage ovarian cancer patients from healthy individuals." (PMID 40836974, 2024). "Already in 2014, this approach was used to engineer Mucin-16 (Muc16) targeting CAR-T cells to additionally secrete IL-12, leading to enhanced CAR-T-cell proliferation and prolonged persistence in an IFN-γ-dependent manner in ovarian cancer in vivo models." (PMID 39711794, 2024). "Like MUC16, MSLN is over-expressed in ovarian cancer with limited expression in normal tissues." (PMID 40836974, 2024). "Due to these limitations, MUC16 as a standalone marker for ovarian cancer detection is not recommended." (PMID 40836974, 2024).
ovarian carcinoma (continued). "Besides, TNFα coordinated with IFNγ to promote MUC16 (CA125) expression in breast and ovarian cancer via the NF-κB signaling axis." (PMID 38166970, 2024). "The human ovarian cancer cell line OVCAR3 is reported to express high levels of MUC16 whereas SKOV3 does not." (PMID 38225646, 2024). "While the immunosuppressive microenvironment of ovarian cancer has been a barrier in their implementation, several early phase clinical trials are currently evaluating CAR-T cell therapies targeting mesothelin, folate receptor a, HER2, MUC16, and B7H3." (PMID 38667465, 2024). "The results showed that similar to the stimulation of ovarian cancer organoids, the proportions of CD11b+, CD66b+, and ICAM-1+ neutrophils in each case of neutrophils were significantly increased after MUC16 treatment for 24 h, while the proportions of CXCR4+ neutrophils were decreased slightly." (PMID 37644468, 2023). "Later, they developed other versions of MUC16-CART with additional modifications, such as 4H11-scFv-fused with IL12, or fused with PD-1 blocking scFv, which have shown a robust anti-tumoral activity to ovarian cancer cell line in preclinical studies." (PMID 37509200, 2023). "The tumor specificity of MUC12 and FLG is not strong, and the early diagnosis of MUC16 in ovarian cancer is not satisfactory." (PMID 37024829, 2023). "Mucin-16 (MUC16), also known as CA-125, is another type 1 transmembrane glycoprotein, routinely used as a tumor marker in ovarian cancer and found in the epithelia of several organs such as the trachea, the ocular surface, the abdominal cavity, and the female reproductive tract." (PMID 35389164, 2022). "Since the MUC16 antibody is well established in routine clinical practice for ovarian cancer, its applicability in CCA diagnosis is ensured without additional effort." (PMID 36230626, 2022). "Owing to the success of cervical and breast cancer screening, as well as the rather modest increase in survival from improved treatment, there have been fervent efforts to boost ovarian cancer survival via screening using CA125, an epitope of MUC16, a large glycoprotein marker." (PMID 33920983, 2021). "Additionally, MUC-16 (CA125), which is primarily upregulated in ovarian cancer cells, binds to Siglec-9-positive leukocytes via α2,3-linked sialic acids." (PMID 34827170, 2021). "In addition, it has been noted that these tumors express low levels of ovarian cancer marker genes (MUC1, MUC16, KLK6, KLK7, and KLK8) and high expression of the developmental transcription factors HMGA2 and SOX1." (PMID 33669749, 2021). "Conversely, known ovarian cancer targets MUC16 and MSLN were not epithelial-restricted and were expressed in both the fibroblast population (12.4% MUC16+, 53.1% MSLN+) and the malignant epithelial cell population (51.3% MUC16+, 78.5% MSLN+)." (PMID 34290299, 2021). "Although MUC16 is an oncogene that plays an important role in the development and progression of ovarian cancer, the regulation of MUC16 expression is not well characterized." (PMID 31039761, 2019). "TNFα (25 ng/ml), which has been previously reported to stimulate MUC16 expression in breast and ovarian cancer cells, failed to increase MUC16 protein expression in HPMCs." (PMID 31039761, 2019). "Since only a few early-stage ovarian carcinomas can be diagnosed, it is difficult to predict the disease progression using standard clinical or pathological prognostic factors, such as grade, stage, or expressions of CA125/MUC16." (PMID 31023965, 2019). "The CT antibodies (5E6, 3H1) and anti-tandem repeat antibody (M11) did not exhibit binding on OVCAR-5 cells, another ovarian cancer cell line that expresses low levels of MUC16." (PMID 29708979, 2018). "Our study provides a novel gene delivery system using a MUC16 promoter trigger and FSH peptide-mediated active targeting in ovarian cancer, and this system may be a promising strategy for specific genetic therapeutic delivery." (PMID 29542355, 2018).
ovarian carcinoma (continued). "Furthermore, the antitumor effects of the nanoparticle complexes with dual modifications of the MUC16 promoter and FSH peptide were evaluated in ovarian cancer in vitro and in vivo." (PMID 29542355, 2018). "In both in vitro and in vivo experiments, MSC-derived Meso64-TR3 was far more potent on MUC16-expressing ovarian cancer compared to its non-targeted TR3 counterpart." (PMID 29267342, 2017). "This assay outperformed the MUC16 and HE4 assays in the diagnosis of ovarian cancer." (PMID 26509158, 2015). "We conclude that the carboxy-terminal portion of the MUC16/CA125 protein is oncogenic in NIH/3T3 cells, increases invasive tumor properties, activates the AKT and ERK pathways, and contributes to the biologic properties of ovarian cancer." (PMID 25965947, 2015). "While these adhesion functions have been suggested to be critical in MUC16-related biology and adverse outcome, these studies do not explain all of the observed changes in ovarian cancer cell behavior." (PMID 25965947, 2015). "Taken together, this analysis demonstrates that MUC16 expression has an adverse impact on the survival of patients with ovarian cancer and confirms the negative biologic effects of MUC16 expression identified in our preclinical models." (PMID 25965947, 2015). "Despite being nonspecific and unreliable for diagnosing early stage ovarian cancer, monitoring serum MUC16 together with ultrasonography is a standard procedure for detection of ovarian malignancies." (PMID 26509158, 2015). "Contribution of MUC16-selectin interaction to ovarian cancer progression or metastasis is not known." (PMID 24886523, 2014). "Ovarian cancer cells are therefore likely to be protected from NK cell and monocyte attack due to the negative signaling induced via MUC16-Siglec-9 interaction." (PMID 24886523, 2014). "In a recently reported phase I clinical trial of DMU-C5754A (an anti-MUC16 antibody/mitotic toxin MMAE drug conjugate), objective responses were observed in 5 out of 44 patients diagnosed with advanced/recurrent platinum-resistant ovarian cancer." (PMID 24447304, 2014). "Mucin 16 (MUC16) is a type I transmembrane protein, the extracellular portion of which is shed after proteolytic degradation and is denoted as CA125 antigen, a well known tumor marker for ovarian cancer." (PMID 22949868, 2012). "CA125 (MUC16), originally thought to be an indicator of ovarian cancer, is now known to be quite non-specific as well as to lack the sensitivity to detect stage I disease." (PMID 20350313, 2010). "RT-PCR of peripheral blood mononuclear cells (PBMC) from ovarian cancer patients and other in vitro experiments, reported in our previous study, showed that immune cells do not express MUC16." (PMID 20497550, 2010). "The only widely used ovarian cancer marker CA125 lacks specificity (CA125 or MUC16 is not present on the U95Av2 array)." (PMID 14760385, 2004). "Our study provides support for further optimization and testing of MUC16-targeted VLP vaccines based upon papillomavirus L1, including the safety of the approach in animals and its ability to prevent and limit the growth of mouse and human models of ovarian cancer." (PMID 38225646, 2024). "To date, targeting MUC16/CA-125 for ovarian cancer treatment has not been successful." (PMID 34503075, 2021). "Because we have previously shown that ascites-induced Akt activation in ovarian cancer cells is mediated by αvβ5 integrin and focal adhesion kinase (FAK) activation, we determined whether ascites that strongly promote MUC16 expression and secretion could induce FAK activation in HPMCs." (PMID 31039761, 2019). "The lack of stimulation of MUC16 release by benign peritoneal fluids suggest that factors differentially expressed between ovarian cancer ascites and benign peritoneal fluids could be responsible for ascites-induced stimulation of MUC16 expression and release." (PMID 31039761, 2019).
ovarian carcinoma (continued). "Constitutive synthesis and shedding of MUC16 glycoprotein have been previously reported in HPMC monolayer cultures suggesting that HPMCs may be an important source of the MUC16 found in the ascites and sera of women with ovarian cancer." (PMID 31039761, 2019). "The presence of MUC16 CT has never before been biochemically described in ovarian cancer." (PMID 29708979, 2018). "However, we strongly believe that this model of drug delivery can also be applied to ovarian cancer due to our prior success in developing soluble, mesothelin-TR3 fusion proteins (MesoTR3 and Meso64TR3), which bind with high affinity to MUC16, highly expressed on ovarian cancer cells." (PMID 29267342, 2017). "However, bioinformatics analysis of MUC16 expression and mutations available through The Cancer Genome Atlas (TCGA) does not support a major effect of MUC16 on overall survival in ovarian cancer patients." (PMID 24886523, 2014). "The promoter of mucin 16 (MUC16), also known as CA125, might be a potential tool to drive tumor-localized gene expression in ovarian cancer cells since CA125 is overexpressed in 80% of ovarian carcinomas, and serum CA125 is used as a marker for the monitoring of the treatment response." (PMID 29542355, 2018). "Since MUC16 can be overexpressed in a variety of non-ovarian cancers and benign diseases, the CA125 assay shows poor specificity for ovarian cancer diagnosis and frequently presents false positives." (PMID 37455827, 2023). "Two mAbs against MUC16, oregovomab and abagovomab, have been trialled separately in phase III clinical trials in patients with ovarian cancer, but neither showed significantly improved clinical outcomes compared to controls." (PMID 32937961, 2020). "In our experiments with ovarian cancer cell lines, we have observed that OC125 weakly binds to the surface of cells—SKOV-3 and A2780—that are generally considered to be non-expressors of MUC16." (PMID 24886523, 2014). "After the MUC16 promoter was introduced into the FSH peptide-conjugated gro-α shRNA nanoparticles, tumor growth was significantly inhibited in a nude mouse model bearing ovarian cancer, and no obvious toxic effects were observed." (PMID 29542355, 2018). "In addition to MUC16, MUC13 may be useful in detecting some subtypes of nonserous ovarian carcinomas and early-stage ovarian carcinomas (stages I and II)." (PMID 37664708, 2023). "The nanoparticle complex containing MUC16 promoter-driven gro-α shRNA and FSH peptides had the ability to decrease gro-α protein secretion in ovarian cancer cells and block tumor growth without obvious toxic effects in a nude mouse model bearing ovarian cancer." (PMID 29542355, 2018).